P4HA1 (prolyl 4-hydroxylase subunit alpha 1)
Diseases named in the same sentence as P4HA1 in open-access papers (continued):
Sharing a sentence is not in itself a finding about the gene and the disease.
connective tissue disorder (2 papers, 2022). A disease involving the connective tissue. "Previous studies on P4HA1 mainly focused on the congenital connective tissue disorder caused by gene mutation, and the correlation between P4HA1 and tumors has rarely been reported." (PMID 35558559, 2022). "Thus, the P4ha1+/−; P4ha2−/− mouse model recapitulates key aspects of a recently recognized congenital connective tissue disorder with short stature and bone dysplasia caused by biallelic variants of the human P4HA1 gene." (PMID 35720665, 2022). "Our understanding of the roles of C‐P4H activity and individual isoenzymes in human development and tissue homeostasis gained a significant step forward with the recent discovery of the first congenital connective tissue disorder caused by elaborate biallelic pathogenic variants in P4HA1." (PMID 35720665, 2022).
cardiovascular diseases (1 paper, 2024). "The following section will further discuss the role and specific mechanisms of P4HA1 in the context of cardiovascular disease fibrosis." (PMID 39568592, 2024). "Therefore, it is necessary to further expand the research scope and explore the specific roles and mechanisms of P4HA1 in different types of cardiovascular diseases." (PMID 39568592, 2024). "In addition, due to the limitations of research on the mechanism of P4HA1 fibrosis in cardiovascular diseases." (PMID 39568592, 2024). "Therefore, future research should explore the mechanism of action of P4HA1 through various methods such as cell experiments, animal models, clinical cases, and comprehensively analyze other related genes and signals to understand the role of P4HA1 in fibrosis in cardiovascular diseases." (PMID 39568592, 2024).
infection (1 paper, 2024). The state of being infected such as from the introduction of a foreign agent such as serum, vaccine, antigenic substance or organism. "Western blotting confirmed that Ad-P4HA1 infection increased P4HA1 protein levels compared to the control group." (PMID 38238754, 2024). "Western blotting confirmed the upregulation of P4HA1 in the gastrocnemius muscle and ECs following adenovirus Ad-P4HA1 infection." (PMID 38238754, 2024). "Immunofluorescence and Western blotting verified that adenovirus Sh-P4HA1 infection reduced P4HA1 expression in ECs." (PMID 38238754, 2024). "Western blotting confirmed that Ad-shP4HA1 infection effectively downregulated P4HA1 in HUVECs." (PMID 38238754, 2024). "In the non-ECs fraction, Ad-P4HA1 infection slightly increased the P4HA1 protein level but did not change the protein levels of FBP1 and TET2." (PMID 38238754, 2024). "Furthermore, Ad-shP4HA1 infection did not affect protein levels of P4HA1, TET2, and FBP1 in the non-ECs fraction." (PMID 38238754, 2024).
renal disease (1 paper, 2016). "Thus reduction of the P4ha1 mediated compensation in the absence of Wnt5a function aggravates the renal disease phenotype." (PMID 26794322, 2016).
P4HA1 also shares sentences with these, for which no sentence is quoted: bladder cancer (3 papers); lung squamous cell carcinoma (3); Pan (2); squamous cell carcinoma (2); adenocarcinoma (1); adrenocortical carcinoma (1); Alzheimer disease (1); atopic dermatitis (1); atrial fibrillation (1); autism spectrum disorder (1); B-cell lymphoma (1); bladder urothelial carcinoma (1); cholangiocarcinoma (1); chronic myeloid leukaemia (1); coronary atherosclerosis (1); diffuse large B-cell lymphoma (1); head and neck tumors (1); heart failure (1); immune deficiency (1); kidney cancer (1); laryngeal carcinoma (1); Lymphatic Metastasis (1); metastatic disease (1); myopia (1); neurodevelopmental disorder (1); Osteopenia (1); paraganglioma (1); phenylketonuria (1); pheochromocytoma (1); preeclampsia (1).
A further 10 diseases each share a sentence with P4HA1 in 1 paper.